ADGRB1 (adhesion G protein-coupled receptor B1)
Description:
Phosphatidylserine receptor which enhances the engulfment of apoptotic cells. Also mediates the binding and engulfment of Gram-negative bacteria. Stimulates production of reactive oxygen species by macrophages in response to Gram-negative bacteria, resulting in enhanced microbicidal macrophage activity. In the gastric mucosa, required for recognition and engulfment of apoptotic gastric epithelial cells. Promotes myoblast fusion (By similarity). Activates the Rho pathway in a G protein-dependent manner. Inhibits MDM2-mediated ubiquitination and degradation of DLG4/PSD95, promoting DLG4 stability and regulating synaptic plasticity (By similarity). Required for the formation of dendritic spines by ensuring the correct localization of PARD3 and TIAM1 (By similarity). [Vasculostatin-120]: Inhibits angiogenesis in a CD36-dependent manner. [Vasculostatin-40]: Inhibits angiogenesis.
Synonyms: BAI1; GDAIF
Tractability: Antibody: UniProt places it where antibodies can reach, with high confidence; its Gene Ontology location is reachable by antibodies, with high confidence; UniProt predicts a signal peptide or a membrane-spanning region. PROTAC: UniProt records ubiquitination sites on it.
Gene: Protein-coding gene on chromosome 8 (142,449,430 to 142,545,009, forward strand). Ensembl gene ENSG00000181790.
Subcellular location: Cell membrane; Cell projection, phagocytic cup; Cell junction, focal adhesion; Cell projection, dendritic spine; Postsynaptic density; Secreted (Vasculostatin-120); Secreted (Vasculostatin-40)
Gene Ontology:
Molecular function: G protein-coupled receptor activity; protein binding; lipopolysaccharide binding; phosphatidylserine binding; PDZ domain binding; transmembrane signaling receptor activity
Biological process: apoptotic cell clearance; engulfment of apoptotic cell; negative regulation of angiogenesis; negative regulation of endothelial cell migration; positive regulation of reactive oxygen species biosynthetic process; axonogenesis; cell adhesion; defense response to Gram-negative bacterium; G protein-coupled receptor signaling pathway; negative regulation of cell population proliferation; negative regulation of protein catabolic process; negative regulation of protein ubiquitination; peripheral nervous system development; phagocytosis, recognition; positive regulation of myoblast fusion; regulation of synaptic plasticity; signal transduction; cell surface receptor signaling pathway; phagocytosis, engulfment
Cellular component: extracellular region; perinuclear region of cytoplasm; plasma membrane; cell-cell junction; dendrite; focal adhesion; membrane; phagocytic cup; postsynaptic density; cell junction; dendritic spine
Genetic constraint (gnomAD): Loss-of-function variants: 34 observed, 121.54 expected, observed/expected ratio (o/e) 0.28, 90% interval 0.21 to 0.37. The synonymous counts are far from expectation, so gnomAD's model fits this gene poorly and the ratio says little. Missense variants: 1,680 observed, 1,880.8 expected, observed/expected ratio (o/e) 0.89, 90% interval 0.86 to 0.93. Synonymous variants: 1,029 observed, 828 expected, observed/expected ratio (o/e) 1.24, 90% interval 1.18 to 1.31.
Homologues: Orthologues: macaque ADGRB1 (99% identical), chimpanzee ADGRB1 (96% identical), mouse Adgrb1 (94% identical), rat AABR07058422.1 (94% identical), pig ADGRB1 (93% identical), guinea pig ADGRB1 (93% identical), dog ADGRB1 (90% identical), tropical clawed frog adgrb1 (70% identical), zebrafish adgrb1a (65% identical), zebrafish adgrb1b (48% identical). Paralogues in human: ADGRB3 (46% identical), ADGRB2 (41% identical), ADGRL2 (14% identical), ADGRL3 (14% identical), ADGRL1 (14% identical), ADGRA2 (12% identical), ADGRA3 (12% identical), ADGRG4 (11% identical), ADGRE5 (11% identical), ADGRF5 (11% identical), ADGRE2 (10% identical), ADGRG6 (10% identical), and 30 more.
Diseases named in the same sentence as ADGRB1 in open-access papers:
ADGRB1 is named in the same sentence as 54 diseases in open-access papers, as found by Europe PMC text mining. Sharing a sentence is not in itself a finding about the gene and the disease. The quoted sentences say what the papers report.
glioblastoma (15 papers, 2002 to 2025). The most malignant astrocytic tumor (WHO grade IV). "Interestingly, glioblastoma, gastric cancer, and colorectal cancer, which are dominant in males, are associated with ADGRB1, and schizophrenia and autism, which are also dominant in males, are associated with SLC6A12." (PMID 27561550, 2016). "ADGRB1 encodes for brain-specific angiogenesis inhibitor 1 (BA1) which has an anti-angiogenic role and is downregulated in glioblastoma and metastatic colorectal cancer." (PMID 35851095, 2022). "siRNAs targeting ADGRB1 exon 23, but not exon 10, reduced the expression of ~ 75 kDa BAI1 isoforms in medulloblastoma (DAOY) and glioblastoma (LN319) cell lines." (PMID 38941066, 2025).
colitis (9 papers, 2017 to 2025). Inflammation of the colon. "Adgrb1-deficient mice had more pronounced colitis and lower survival, with many uncleared apoptotic cells and inflammatory cytokines within the colonic epithelium." (PMID 31130954, 2019). "Notably, transgenic overexpression of Adgrb1 in epithelial, but not in myeloid cells, attenuated colitis severity, suggesting that BAI1 mediates clearance of apoptotic corpses within the colonic epithelium." (PMID 31130954, 2019).
breast carcinoma (7 papers, 2015 to 2023). "The ADGRB1 variant was also present at increased frequencies among individuals with a lymphoid neoplasm and breast cancer diagnosis (25.0%)." (PMID 36199081, 2022).
medulloblastoma (7 papers, 2021 to 2025). A malignant, invasive embryonal neoplasm arising from the cerebellum. "Recent studies revealed that the adhesion G-protein-coupled receptor B1 (ADGRB1) gene undergoes epigenetic silencing in medulloblastoma." (PMID 34066495, 2021).
ovarian carcinoma (3 papers, 2016 to 2022). A malignant neoplasm originating from the surface ovarian epithelium. "In addition to ADRB1, BRCA1-deficient ovarian cancer cells also express high levels of other factors related to catecholamine-adrenoceptor-cAMP pathway regulation, such as the adenylate cyclase ADCY2 and G protein-coupled receptor ADGRB1." (PMID 35517499, 2022).
Parkinson disease (2 papers, 2022 to 2023). A progressive degenerative disorder of the central nervous system characterized by loss of dopamine producing neurons in the substantia nigra and the presence of Lewy bodies in the substantia nigra and locus coeruleus. "Overexpression of ADGRB1 resulted in decreased levels of nuclear condensations associated with cell death and Parkinson's disease, suggesting that ADGRB1 can prohibit cell death in the neurodegenerative pathway (a potential therapeutic target) of Parkinson’s disease." (PMID 36157580, 2022). "Decreased levels of ADGRB1 are reported in patients diagnosed with Parkinson’s disease." (PMID 36157580, 2022).
schizophrenia (2 papers, 2016 to 2022). A major psychotic disorder characterized by abnormalities in the perception or expression of reality. "Another interesting variant was identified in affected siblings MC-24-3 and MC-24-4, in an enhancer region that interacts with the promoters of TSNARE1, a gene associated with schizophrenia, and ADGRB1, a critical regulator of spine and synapse development." (PMID 35190550, 2022).
hepatocellular carcinoma (1 paper, 2021). A malignant tumor that arises from hepatocytes. "ADGRB1 identified in CCs was a newly recognized driver gene that was found in Aflatoxin-Associated Hepatocellular Carcinoma, suggesting that ADGRB1 play a vital role in cancer pathogenesis." (PMID 34221990, 2021).
tumor (32 papers, 2002 to 2026). "Brain angiogenesis inhibitor-1 (BAI1/ADGRB1), another cancer-associated aGPCR, is enriched in the brain and has been associated with tumor angiogenesis." (PMID 29594040, 2018). "This is in agreement with the previous findings of Kudo and coworkers who studied the potential of ADGRB1 as an anti-angiogenic factor in RCC based on the known inverse correlation of its expression with vascular density in other tumor types." (PMID 29468160, 2018). "They demonstrated in an in vivo tumor model (subcutaneous inoculation of the RCC cell line Renca) that ADGRB1 overexpression in Renca reduced tumor growth due to reduced microvessel density which was associated with reduced VEGF expression levels." (PMID 29468160, 2018). "Yet, there are also a large variety of other factors that control tumor angiogenesis including Adgrb1." (PMID 29468160, 2018). "Furthermore, the brain-specific angiogenesis inhibitor 1 (ADGRB1) is an important tumor suppressor in numerous malignancies, including lung cancer." (PMID 36216799, 2022). "Among 15 genes in the signature, except four genes, RAB27A, ADGRB1, MT1F, and TPT1, the remaining were differentially expressed between tumor and normal tissues." (PMID 33329725, 2020). "ADGRB1/BAI1 belongs to the ADGRB subfamily whose three members were named brain-specific angiogenesis inhibitors (BAIs) based on their ability to inhibit angiogenesis and tumor formation." (PMID 36982575, 2023).
cancer (22 papers, 2002 to 2025). A tumor composed of atypical neoplastic, often pleomorphic cells that invade other tissues. "COSMIC database showed that ADGRB1 was a moderately over-expressed in 6.84% (21/307) of CCs, and there were many types of variants, including somatic mutations, CNVs and dysregulation in ADGRB1 in a quantity of cancers." (PMID 34221990, 2021). "Genes whose median expression was below the threshold in more than half of the cancer types were common in cohorts A and B (ADGRB1, IGF1, RPRM, TP53AIP1)." (PMID 36964217, 2023).
neurological diseases (5 papers, 2018 to 2025). "The genes with the highest number of connections with other diseases were PAK3, GRIA3, and ADGRB1 associated with eight, six, and six neurological diseases, respectively." (PMID 33922640, 2021).
ADGRB1 also shares sentences with these, for which no sentence is quoted: glioma (9 papers); lung carcinoma (5); pancreatic cancer (4); renal cell carcinoma (4); brain tumors (3); gastric cancer (3); neurodegenerative disease (3); autism (2); colon cancer (2); colorectal cancer (2); leukemia (2); lung adenocarcinoma (2); pancreatic adenocarcinoma (2); acute lymphoblastic leukemia (1); adenocarcinoma (1); astrocytomas (1); auditory neuropathy (1); bacterial infection (1); brain arteriovenous malformation (1); brain astrocytoma (1); brain cancer (1); breast tumors (1); cerebrovascular diseases (1); cervical cancer (1); cholangiocarcinoma (1); frontoparietal polymicrogyria (1); gastric adenocarcinoma (1); infection (1); injury (1); Insulin resistance (1).
A further 13 diseases each share a sentence with ADGRB1 in 1 paper.